BATF (basic leucine zipper ATF-like transcription factor)
Diseases named in the same sentence as BATF in open-access papers (continued):
Sharing a sentence is not in itself a finding about the gene and the disease.
anaplastic large cell lymphoma (4 papers, 2020 to 2022). Anaplastic large cell lymphoma (ALCL) is a rare and aggressive peripheral T-cell non-Hodgkin lymphoma, belonging to the group of CD30-positive lymphoproliferative disorders, which affects lymph nodes and extranodal sites. "In anaplastic large-cell lymphoma and non–small-cell lung cancer, elevated BATF expression was also reported, consistent with our study." (PMID 35573731, 2022). "In tumors, abnormal BATF expression was found in anaplastic large-cell lymphoma and non-small-cell lung." (PMID 35573731, 2022). "A factor repressed upon PRMT5 inhibition, is the Basic Leucine Zipper ATF-like Transcription Factor, BATF3, which was shown to be required for proliferation in Hodgkin lymphoma, anaplastic large cell lymphoma as well as adult T cell leukemia/ lymphoma." (PMID 32555249, 2020).
asthma (4 papers, 2019 to 2025). "In an allergic asthma model, BATF-deficient mice exhibited reduced symptoms of asthma, including a decrease in eosinophils and lymphocytes, and a significant reduction in cytokines such as IL-4, IL-5, and IL-13 in the lungs." (PMID 39876010, 2025). "Overexpression of Foxp2 in an asthma model inhibited Th9 differentiation and reduced IRF4 and BATF expression." (PMID 40909266, 2025). "The absence of BATF significantly reduces the expression of Th9 cell-related genes, as evidenced by mouse models demonstrating decreased incidence of experimental asthma." (PMID 39876010, 2025). "It has been reported that BATF transcription is significantly higher in the PBMC of children with recurrent asthma who have not been treated with corticosteroid." (PMID 31024538, 2019).
gastric cancer (4 papers, 2019 to 2025). A primary or metastatic malignant neoplasm involving the stomach. "We found that BATF was not only associated with immune-cell infiltration, but also associated with cell activation in both gliomas and gastric cancer." (PMID 35573731, 2022). "For instance, certain researchers have detected that METTL3 methylation of basic leucine zipper ATF-like transcription factor (BATF) mRNA inhibits its expression in gastric cancer (GC), and low expression of BATF mRNA is significantly associated with postoperative recurrence of GC." (PMID 39054967, 2024). "Additionally, the expression of YAP1, FOXM1, KRAS, and BATF genes were decreased in gastric cancer cells by treatment of UA." (PMID 31547587, 2019).
myeloid leukemia (4 papers, 2010 to 2020). A clonal proliferation of myeloid cells and their precursors in the bone marrow, peripheral blood, and spleen. "It was reported that in M1 mouse myeloid leukemia cells, forced expression of BATF resulted in a reduced rate of cellular growth." (PMID 20856936, 2010). "As a specific example, STAT3 has been shown to differentially regulate the mRNA expression of BATF in myeloid leukemia but not in normal condition." (PMID 27145341, 2016).
rheumatoid arthritis (4 papers, 2014 to 2025). A chronic, systemic autoimmune disorder characterized by inflammation in the synovial membranes and articular surfaces. "BATF overlaps rheumatoid arthritis and multiple sclerosis susceptibility loci at 14q24.3." (PMID 25170024, 2014). "We highlight six tocilizumab responsive genes (ARID5A, BCL3, PIM1, SOCS3, BATF, MYC) that are associated with IL-6 pathway and known to be perturbed by tocilizumab treatment in rheumatoid arthritis patients." (PMID 35064122, 2022). "Compelling evidence suggests that BATF is involved in the development of multiple sclerosis (MS), rheumatoid arthritis (RA), systemic lupus erythematosus (SLE), experimental autoimmune uveitis (EAU), experimental autoimmune encephalomyelitis (EAE), and inflammatory bowel disease (IBD)." (PMID 39876010, 2025).
Sepsis (4 papers, 2022 to 2024). Sepsis is defined as life-threatening organ dysfunction caused by a dysregulated host response to infection. "This is consistent with literature which have previously identified BATF as part of a transcriptomic signature of neonatal sepsis, albeit from whole blood, and have incorporated this gene into sepsis scores to predict early-life sepsis." (PMID 38195661, 2024). "Akin to our scRNA-seq analysis of CD3+ αβ-T cells, we observed that BATF and AREG were among the top differentially expressed genes within the B cell cluster during Enterobacter MCS versus its temporally closest pre-sepsis timepoint." (PMID 38195661, 2024).
acute myeloid leukemia (3 papers, 2024 to 2025). Acute myeloid leukemia (AML) is a group of neoplasms arising from precursor cells committed to the myeloid cell-line differentiation. "However, the associations between BATF expression and prognoses in acute myeloid leukaemia (AML) patients and their immunological effects remain unclear." (PMID 39872530, 2024). "BATF is a core transcription factor that leads to impaired natural killer (NK) cell killing capacity in acute myeloid leukemia." (PMID 40874179, 2025).
allergic asthma (3 papers, 2021 to 2025). A asthma with a basis in a pathological type I hypersensitivity reaction. "As a proof of concept, mutations within BATF prevents the development of allergic asthma for Batf promotes the production of pro-allergic IL-4 by Tfh cells in mouse." (PMID 35812386, 2022). "Studies have demonstrated that BATF is essential for the function of Th9 cells, particularly in the context of allergic asthma." (PMID 39876010, 2025). "Besides, BATF inhibition can ameliorate the pathophysiologic responses in allergic asthma acting as the important transcription factor by regulating T and B-cell differentiation." (PMID 33509250, 2021). "In addition, BATF, together with IRF4 and STAT, binds to Il-4 CNS2 to trigger IL-4 expression and boost Tfh cell differentiation, which prevents allergic asthma and peripheral lymphomas." (PMID 35812386, 2022).
atherosclerosis (3 papers, 2021 to 2023). A disease characterized by the build-up of fatty material and calcium deposition in the arterial wall resulting in partial or complete occlusion of the arterial lumen. "One studies have shown that after in vitro and in vivo injection of endotoxin and LPS, six candidate genes (BATF, BID, C3aR1, IL1RN, SEC61B and SLC43A3) were identified to be associated with inflammation and atherosclerosis." (PMID 36303246, 2022). "Up-regulated DEGs of this gene signature included T-cell development, growth and proliferation genes (BATF, CCL5, CD2, EOMES) and F2R, a recognized genetic locus influencing clinical CVD and atherosclerosis development." (PMID 37205656, 2023).
Autoimmunity (3 papers, 2013 to 2021). The occurrence of an immune reaction against the organism's own cells or tissues. "The dramatic consequences of altering BATF expression in vivo provides evidence that BATF functions to coordinate immune system activities critical in autoimmunity, inflammation and the host response to pathogens." (PMID 23537103, 2013).
B-Cell Lymphoma (3 papers, 2014 to 2023). "A pool of important genes involved in B-cell development, oncogenesis, cell cycle regulation, and cell death including BATF, LIMD1, CFLAR, PIM2, and CCND2 are common signatures associated with IRF4 in non-Hodgkin B cell lymphomas." (PMID 25207815, 2014).
colorectal cancer (3 papers, 2021 to 2024). A primary or metastatic malignant neoplasm that affects the colon or rectum. "BATF is a transcription factor whose upregulation was detected in patients with ulcerative colitis (UC) and colorectal cancer (CRC)." (PMID 38495883, 2024). "Recently a study has found that increased expression of BATF, a significant positive correlation that existed with PDCD1 expression, may suppress CD8+ T function and affect the development of colorectal cancer." (PMID 34178621, 2021).
COVID-19 (3 papers, 2021 to 2025). A disease caused by infection with severe acute respiratory syndrome coronavirus 2. "Studies focusing on COVID-19 patients have identified sustained accessibility at exhaustion-related genes (e.g., TOX, Basic Leucine Zipper ATF-Like Transcription Factor (BATF)) and reduced accessibility at effector loci, even in convalescent phases." (PMID 41235245, 2025). "In agreement with the fact that upregulated gene signature in COVID-19 cancer patients is enriched for interferon-regulated genes, their promoters are bound by key regulators of interferon gene expression, IRF, STAT, and BATF TFs." (PMID 34716309, 2021).
glioma (3 papers, 2021 to 2024). A benign or malignant brain and spinal cord tumor that arises from glial cells (astrocytes, oligodendrocytes, ependymal cells). "Multivariate Cox analysis revealed that genes such as PILRA, LILRB2, and BATF were independent prognostic factors for glioma patients." (PMID 34540893, 2021).
helminth infections (3 papers, 2022 to 2025). "In murine models of worm infection, BATF deficiency leads to impaired Tfh and Th2 cell production, as well as diminished cytokine production, including IL-4 and IL-13, by CD4+T cells." (PMID 39876010, 2025). "In worm infection models treated with IL-25, BATF deficiency impairs iILC2 cell production." (PMID 39876010, 2025). "Previous research has indicated that the BATF transcription factor is key in the generation of Th2 cells and follicular helper T cells during helminth infections." (PMID 38786064, 2024). "In studies involving worm infections, IRAK-2 (interleukin-1 receptor-associated kinase-like 2) has been shown to enhance Th17 cell development by augmenting IL-1-induced activation of RORγT and BATF, which may contribute to disease exacerbation." (PMID 39876010, 2025). "During helminth infections, another AP-1 family molecule, basic leucine zipper ATF-like transcription factor (BATF), induces IL-4 and IL-13 in ILC2s32." (PMID 36109558, 2022).
hepatocellular carcinoma (3 papers, 2015 to 2024). A malignant tumor that arises from hepatocytes. "dissected hepatocellular carcinoma heterogeneity and found that an immunosuppressed subtype characterized by high expression of immunosuppressive genes contributes to an immunosuppressive microenvironment, with BATF and a myeloid‐derived suppressor cell‐like macrophage subtype playing key roles." (PMID 39580787, 2024).
multiple sclerosis (3 papers, 2014 to 2021). A progressive autoimmune disorder affecting the central nervous system resulting in demyelination. "And early growth response gene-2 (Egr-2) is an intrinsic regulator that controls Th17 differentiation by inhibiting BATF activation, which may be important in controlling the development of multiple sclerosis." (PMID 35126277, 2021).
allergic disease (2 papers, 2025). An immune response that occurs following re-exposure to an innocuous antigen, and that requires the presence of existing antibodies against that antigen. "GWAS data further strengthen the link between these genes and diseases, with BATF, CEBPA, and ETS1 associated with allergic diseases, and PTPN22, ETS1, PTPN11, and BATF linked to RA." (PMID 40839671, 2025).
colon cancer (2 papers, 2020 to 2022). "Basic leucine zipper transcription factor, ATF-like (BATF) was an important transcription factor regulating differentiation of early effector CD8+ T cells and was a prognostic indicator for patients with colon cancer." (PMID 35651784, 2022).
dermatitis (2 papers, 2017 to 2025). An inflammatory process affecting the skin. "Th17 cell-associated genes, (i.e., S100a8, CAMP, BATF, IL-23A, LCN2, and HIF-1α) highly expressed in Nfkbiz−/− mice with dermatitis, were downregulated after antibiotic treatments." (PMID 28740238, 2017). "Transcriptomic analysis and machine-learning models enable patient stratification, allowing for the identification of biomarkers such as ADAM8, CD47, BATF, SELE, IL-37 that may aid in diagnosis and differentiating ACD from other forms of dermatitis." (PMID 40181807, 2025).
latent infection (2 papers, 2016 to 2020). "Furthermore, PD-1 has been suggested to contribute to HIV-1 disease progression and latent infection through a variety of mechanisms, including the upregulation of the master transcription factor BATF that has been associated with T-cell dysfunction." (PMID 32537473, 2020).
lung cancer (2 papers, 2022 to 2024). A malignant neoplasm involving the lung. "In non–small-cell lung cancer, BATF knockdown suppressed tumor cell proliferation, while it promoted cell apoptosis." (PMID 35573731, 2022).
lupus (2 papers, 2020 to 2025). "In spontaneous lupus mouse models, BATF protein and RNA levels are significantly increased, particularly in the kidneys, where BATF expression positively correlates with RORγT and IL-17 levels." (PMID 39876010, 2025). "Non-classical memory B cells (ATM) in active lupus patients show increased BATF expression and contribute to disease progression." (PMID 39876010, 2025).
melanoma (2 papers, 2021 to 2024). A malignant, usually aggressive tumor composed of atypical, neoplastic melanocytes. "We have additionally shown that by overexpressing BATF in CD8+ T cells, we can enhance CD8+ T cell infiltration, effector differentiation, and function in melanoma." (PMID 33809259, 2021).
type 1 diabetes (2 papers, 2014 to 2025). "Additionally, GWAS have demonstrated that BATF is highly enriched in susceptibility genes for type 1 diabetes (T1D)." (PMID 39876010, 2025).
brain injury (1 paper, 2025). Acute and chronic (see also brain INJURIES, CHRONIC) injuries to the brain, including the cerebral hemispheres, CEREBELLUM, and brain STEM. "In microglia of acute brain injury (TBI) patient/mouse model, m6A levels and METTL3 protein expression were significantly upregulated, which then promoted BATF protein expression by stabilizing BATF mRNA." (PMID 40236697, 2025).
chordoma (1 paper, 2022). Chordomas are rare malignant tumors arising from embryonic remnants of the notochord in axial skeleton. "Additionally, BATF, ACTR3C, and FGFBP2 have been implicated in cancers other than chordomas." (PMID 36439461, 2022).
Crohn disease (1 paper, 2025). A gastrointestinal disorder characterized by chronic inflammation involving all layers of the intestinal wall, noncaseating granulomas affecting the intestinal wall and regional lymph nodes, and transmural fibrosis. "Seven shared risk genes (CD40, PTPN22, CD226, BATF, PRKCB, RasGRP1, and PTPN2) are involved in cytokine pathways linked to Crohn’s disease." (PMID 40839671, 2025).
endometrial cancer (1 paper, 2025). Primary or metastatic malignant neoplasm involving the endometrium (mucous membrane that lines the endometrial cavity). "This study is the first to explore the prognostic significance and immune activation roles of BATF, CD3G, KIAA1755 and CCL5 in endometrial cancer." (PMID 40356925, 2025).
endometriosis (1 paper, 2020). The growth of functional endometrial tissue in anatomic sites outside the uterine body. "At the same time, we calculated the diagnostic value of two hub DETFs (RUNX2 and BATF) for endometriosis." (PMID 33490107, 2020). "The results showed that RUNX2 and BATF were characterized by high specificity and sensitivity in the diagnostic of endometriosis." (PMID 33490107, 2020). "RUNX2 and BATF also had high diagnostic value in endometriosis." (PMID 33490107, 2020). "The Receiver Operating Characteristic (ROC) analysis was used to evaluate the sensitivity and specificity of RUNX2 and BATF for the diagnosis of endometriosis." (PMID 33490107, 2020). "By the PPI analysis, we found two hub TFs (RUNX2 and BATF) and they had significant differences in the analysis of different phases of the endometrium and the analysis of infertile and fertile females with endometriosis." (PMID 33490107, 2020). "Therefore, we had reasons to speculate that RUNX2 and BATF also played a role in the mechanism of endometriosis." (PMID 33490107, 2020).
eosinophilia (1 paper, 2019). "Abolished GATA3, IRF4, and BATF expression in Stim1/2-deficient Tregs may thus explain the type 2 autoimmunity in Stim1/2Foxp3 mice, which is characterized by elevated Th2 cytokines, increased IgE levels and eosinophilia." (PMID 30862784, 2019).
esophageal cancer (1 paper, 2021). A primary or metastatic malignant neoplasm involving the esophagus. "The TCGA RNA-seq database for esophageal cancer patients showed higher expression of ATF5, BATF, and FOSL1 in cancer tissues, which is consistent with the finding of greater expression of these genes in KYSE-30 cells." (PMID 34722266, 2021).
experimental autoimmune encephalomyelitis (1 paper, 2018). An autoimmune demyelinating disease of the central nervous system that is produced experimentally in animals by the injection of homogenized brain or spinal cord in Freund's adjuvant. "This notion is supported by reports that proinflammatory cytokines, such as IL-1β and IL-6, increase BATF expression in naive CD4+ T cells, BATF directly regulates IL-17 expression, and Batf-deficient mice show resistance to experimental autoimmune encephalomyelitis." (PMID 30071881, 2018).
influenza (1 paper, 2019). An acute viral infection of the respiratory tract, occurring in isolated cases, in epidemics, or in pandemics; it is caused by serologically different strains of viruses (influenzaviruses) designated A, B, and C, has a 3-day incubation period, and usually lasts for 3 to 10 days. "Collectively, these data suggest that the aging gene signature regulated by BATF‐MYC‐SATB1 in IL‐7Rαlow EM CD8+ T cells is predictive of influenza vaccine responses in older adults." (PMID 31044512, 2019). "We observed that older adults who developed immune responses to influenza vaccine had increased aging signature genes including those targeted by MYC, BATF, and/or SATB1 compared to older adults who were vaccine nonresponders." (PMID 31044512, 2019).
kidney clear-cell carcinoma (1 paper, 2021). "BATF in B lymphocytes and SMAD in monocytes might be involved in the dysregulation of B7-H7 in kidney clear-cell carcinoma." (PMID 33800752, 2021).
neuroblastoma (1 paper, 2024). Neuroblastoma (NB) is the most common solid, extracranial childhood tumor. "Six characteristic genes (BATF, CXCR3, GIMAP5, GPR18, ISG20, and IGHM) were identified by machine learning, and these genes are associated with multiple immune-related pathways and immune cells in neuroblastoma." (PMID 39559348, 2024). "BATF, CXCR3, GIMAP5, GPR18, IGHM have lower expression in high-risk neuroblastoma patients." (PMID 39559348, 2024). "BATF, CXCR3, GIMAP5, GPR18, ISG20, and IGHM may serve as biomarkers that reflect the conditions of the immune microenvironment of neuroblastoma and hold promise in guiding neuroblastoma treatment." (PMID 39559348, 2024).
Pleural effusion (1 paper, 2025). The presence of an excessive amount of fluid in the pleural cavity. "More importantly, compared to the Tregs in the pleural effusion of HP, the Tregs in the MPE of LCP exhibited higher expression levels of CTLA4, TIGIT, and BATF." (PMID 40959273, 2025).
pulmonary fibrosis (1 paper, 2025). Chronic progressive interstitial lung disorder characterized by the replacement of the lung tissue by connective tissue, leading to progressive dyspnea, respiratory failure, or right heart failure. "Most of the significantly enriched TFs related to pulmonary fibrosis included STAT3, FOXP1, JUNB, ATF3, FosL2, BATF, Fra2 and AP‐1." (PMID 40464702, 2025).
pulmonary TB (1 paper, 2016). "Taken together, although the role of BATF in pulmonary TB has not been studied, we speculate that BATF may be involved in the occurrence of TB via immune system." (PMID 27655333, 2016).